ROR1-AS1 (ROR1 antisense RNA 1)
Gene: Long non-coding RNA gene on chromosome 1 (64,094,379 to 64,171,342, reverse strand). Ensembl gene ENSG00000223949.
Diseases named in the same sentence as ROR1-AS1 in open-access papers:
ROR1-AS1 is named in the same sentence as 4 diseases in open-access papers, as found by Europe PMC text mining. Sharing a sentence is not in itself a finding about the gene and the disease. The quoted sentences say what the papers report.
bladder cancer (1 paper, 2020). "This study aimed to determine the expression and clinical significance of lncRNA ROR1 antisense RNA 1 (ROR1-AS1) from patients with bladder cancer, and to explore the potential role and mechanism underlying ROR1-AS1-related cancer progression." (PMID 31929567, 2020). "Correlation between ROR1 antisense RNA 1 (ROR1-AS1) expression and different clinicopathologic features in 65 cases of bladder cancer patients." (PMID 31929567, 2020).
cervical cancer (1 paper, 2021). A primary or metastatic malignant neoplasm involving the cervix. "Overexpression of lncRNA ROR1AS1 predicts a poor prognosis and promotes cervical cancer metastasis by activating the Wnt/β-catenin/EMT signaling cascade." (PMID 33869042, 2021).
glioma (1 paper, 2022). A benign or malignant brain and spinal cord tumor that arises from glial cells (astrocytes, oligodendrocytes, ependymal cells). "It is not hard to see exosomal lncRNA ROR1-AS1 derived from tumor cells promoted glioma progression via the miR-4686 axis, and the high expression of ROR1AS1 indicated a poor prognosis in glioma patients." (PMID 36438184, 2022).
ROR1-AS1 also shares sentences with these, for which no sentence is quoted: cancer (1 paper).